CCDC12 (coiled-coil domain containing 12)
Synonyms: MGC23918
Tractability: Small molecule: a structure with a bound ligand is known. PROTAC: UniProt records ubiquitination sites on it; ubiquitination databases record sites on it; its protein half-life has been measured.
Gene: Protein-coding gene on chromosome 3 (46,916,634 to 46,982,010, reverse strand). Ensembl gene ENSG00000160799.
Subcellular location (Human Protein Atlas): Nucleoplasm
Pathways (Reactome):
Metabolism of RNA: mRNA Splicing - Major Pathway
Gene Ontology:
Molecular function: protein binding
Cellular component: nucleoplasm; post-mRNA release spliceosomal complex; U2-type spliceosomal complex
Genetic constraint (gnomAD): Loss-of-function variants: 28 observed, 24.45 expected, observed/expected ratio (o/e) 1.15, 90% interval 0.85 to 1.57. The upper end of that interval is the gene's LOEUF score, 1.57, which puts it in group 6 of 6, group 1 being the genes least tolerant of losing a copy. Missense variants: 198 observed, 209.21 expected, observed/expected ratio (o/e) 0.95, 90% interval 0.84 to 1.07. Synonymous variants: 75 observed, 88.75 expected, observed/expected ratio (o/e) 0.85, 90% interval 0.7 to 1.02.
Homologues: Orthologues: chimpanzee CCDC12 (100% identical), dog CCDC12 (94% identical), guinea pig CCDC12 (93% identical), pig CCDC12 (93% identical), macaque CCDC12 (92% identical), rabbit CCDC12 (92% identical), mouse Ccdc12 (90% identical), tropical clawed frog ccdc12 (70% identical), rat Ccdc12 (64% identical), zebrafish ccdc12 (62% identical), Drosophila melanogaster CG15525 (41% identical), Caenorhabditis elegans ccdc-12 (34% identical).
Diseases named in the same sentence as CCDC12 in open-access papers:
CCDC12 is named in the same sentence as 12 diseases in open-access papers, as found by Europe PMC text mining. Sharing a sentence is not in itself a finding about the gene and the disease. The quoted sentences say what the papers report.
colorectal cancer (2 papers, 2022 to 2024). A primary or metastatic malignant neoplasm that affects the colon or rectum. "A genome-wide association study (GWAS) identified colorectal cancer risk single nucleotide polymorphism (SNP) rs1076394 as an expression Quantitative Trait Loci (eQTL) for CCDC12." (PMID 35217636, 2022). "These functions were annotated to suggest a possible role of CCDC12 as a regulator in colorectal cancer." (PMID 35217636, 2022). "Hence, we inferred that rs8180040 may affect the occurrence of colorectal cancer by regulating CCDC12 expression." (PMID 35217636, 2022).
prostate carcinoma (2 papers, 2020 to 2022). A carcinoma that arises from epithelial cells of the prostate gland.
breast tumors (1 paper, 2019). "In primary human breast tumors, the most common ITGB1 isoform 1 A was positively correlated to Suppressor-SFs such as DDX3X and DHX9 while being negatively correlated to Enhancer-SFs such as CCDC12 and FAM50A." (PMID 30940821, 2019).
chronic myeloid leukemia (1 paper, 2022). "CCDC12 has been demonstrated to accelerate the growth of K562 cells by upregulating CD235, ε-globin, and γ-globin in human chronic myeloid leukemia." (PMID 35217636, 2022).
colon adenocarcinoma (1 paper, 2022). "Our team ventured the hypothesis that a complete knockout of CCDC12 might hold promise for treating colon adenocarcinoma, but perhaps it would also cause other dysfunctions as a result of a complete knockout." (PMID 35217636, 2022). "Integrative expression Quantitative Trait Loci (eQTL) analysis found that rs8180040 was significantly associated with Coiled-coil domain containing 12 (CCDC12) in colon adenocarcinoma (COAD) patients." (PMID 35217636, 2022). "In this study, we demonstrated that CCDC12 was highly expressed in colon adenocarcinomas and may affect cancer metastasis by regulating EMT." (PMID 35217636, 2022).
colon cancer (1 paper, 2022). "All these results imply that CCDC12 is a colon cancer-associated oncogene." (PMID 35217636, 2022). "In our study, we proved that CCDC12 was highly expressed in colon cancer tissues by RNA sequencing data from the TCGA database, western blotting of fresh tissues, and IHC of paraffin-embedded tissues." (PMID 35217636, 2022). "Fortunately, Snail-associated animal models also showed the correlation between CCDC12 and Snail, and precisely, CCDC12 regulated the growth and invasion of colon cancer through Snail." (PMID 35217636, 2022). "In in vivo experiments, both knockdown and overexpression of CCDC12 resulted in tumor cells exhibiting a clear transition between epithelial and mesenchymal states, and overexpression of CCDC12 effectively promoted differentiation of colon cancer cells to the mesenchymal state." (PMID 35217636, 2022). "Knockdown of CCDC12 could significantly reduce proliferation, migration, invasion, and tumorigenicity of colon cancer cells, while exogenous overexpression of CCDC12 had the opposite effect." (PMID 35217636, 2022). "CCDC12 was significantly higher in 10 colon cancer tissue samples compared to normal." (PMID 35217636, 2022). "All these findings demonstrated that CCDC12 may regulate EMT of colon cancer cells through Snail located in the nucleus." (PMID 35217636, 2022). "All these results indicated that knockdown of CCDC12 could effectively inhibit colon cancer cell proliferation, invasion, migration, and promote apoptosis in vivo and in vitro, which was related to EMT." (PMID 35217636, 2022). "We suspected that the zinc ion mentioned in the results might be a member of the Snail superfamily and therefore performed a follow-up verification, which indeed turned out to be true, that CCDC12 influences the malignant progression of colon cancer through Snail." (PMID 35217636, 2022). "Based on expression levels of CCDC12 in colon cancer cell lines, HCT116 cell line and CCDC12-knocked SW480 cell line were selected to overexpress CCDC12 (OE-CCDC12 group), with NC group and Vec group as a knockdown." (PMID 35217636, 2022). "CCDC12 plays a significant role in tumorigenesis, development, and invasion of COAD and may affect the epithelial to mesenchymal transformation process of colon cancer cells by regulating the Snail pathway." (PMID 35217636, 2022). "Through real-time quantitative polymerase chain reaction (RT-qPCR) with 5 different colon cancer cell lines and the CCD-18Co as the control, we found CCDC12 was relatively overexpressed in LOVO and SW480 cell lines, hence we reduced their expression levels using sh-CCDC12 RNA." (PMID 35217636, 2022).
platelet disorders (1 paper, 2015). "Furthermore, the NBEAL2 gene which is located near CCDC12 is already recognized in familial platelet disorders with a predisposition to MDS/AML." (PMID 26384344, 2015).
cancer (4 papers, 2016 to 2022). A tumor composed of atypical neoplastic, often pleomorphic cells that invade other tissues. "These annotated functions imply that CCDC12 plays a signaling role in the nucleus, especially in the mis-signaling process of cancer." (PMID 35217636, 2022). "After the knockdown of CCDC12, the number of cancer nodules on the liver of mice was reduced, and IHC showed that the expression of CCDC12 was also downregulated." (PMID 35217636, 2022). "These may suggest that longer transcripts of PABPN1, CCDC12 and ISY1 are important for maintaining cancer cell survival (p < 0.01)." (PMID 36263133, 2022).
tumor (3 papers, 2008 to 2022). "In this study, we demonstrated that high expression levels of CCDC12 in COAD were closely associated with tumor development and aggression." (PMID 35217636, 2022). "And in in vivo experiments, CCDC12 has also been shown to promote transplant tumor growth and liver metastasis, with sections of tumors and liver nodules indeed showing a higher degree of cell malignancy." (PMID 35217636, 2022). "CCDC12 promoted COAD tumor cell proliferation, invasion, migration, and inhibited apoptosis in in vitro and in vivo experiments." (PMID 35217636, 2022). "The MDR included the CCDC12, NBEAL2, SETD2, KIF9 and KLHL18 genes, of which SETD2 was the most significantly underexpressed in tumour cells." (PMID 27282254, 2016).
CCDC12 also shares sentences with these, for which no sentence is quoted: acute myeloid leukaemia (1 paper); entropion (1); small cell lung carcinoma (1).